STAT4 (signal transducer and activator of transcription 4)
Diseases named in the same sentence as STAT4 in open-access papers (continued):
Sharing a sentence is not in itself a finding about the gene and the disease.
autoimmune disease (continued). "Taken together, our data strengthen STAT4 rs7574865 G/T and PTPN22 rs2488457 G/C polymorphisms as susceptibility factors for JIA and provide further evidence for a common origin of autoimmune diseases." (PMID 25781893, 2015). "Among many autoimmune disease-related genes, STAT4, C8orf13–BLK, as well as interferon regulatory factor 5 (IRF5) seem to be the most representative susceptibility genes in the Japanese population." (PMID 24632671, 2014). "Such cumulative associations have been shown in other autoimmune diseases, and now also here, by the discovery of the additive effect of alleles in C8orf13–BLK and STAT4 in increasing the risk for polymyositis/dermatomyositis." (PMID 24632671, 2014). "IFNγ is a cytokine associated with a number of autoinflammatory and autoimmune diseases, due to its role in Th1 cell stimulation, differentiation, and function via STAT1 and STAT4 pathways." (PMID 24405805, 2014). "STAT4 appears to factor strongly in the pathogenesis of this and other autoimmune diseases and requires continued study." (PMID 24648611, 2014). "STAT4 also mediates the IL-23-dependent expansion of Th17 cells, contributing to autoimmune diseases." (PMID 22729903, 2012). "Recent studies demonstrated an association of STAT4 variants with systemic lupus erythematosus (SLE) and rheumatoid arthritis (RA), indicating that multiple autoimmune diseases share common susceptibility genes." (PMID 20454450, 2010). "TRAF1-C5 and STAT4 polymorphisms have been shown to associate with RA and SLE, and also with some other autoimmune diseases." (PMID 20479942, 2010). "The transcription factor STAT4 is a therapeutic target for autoimmune diseases." (PMID 40067743, 2025). "Finally, the STAT4 gene participates in the differentiation and proliferation of Th1 and Th17 cells, playing a crucial role in the development of autoimmune diseases, including RA." (PMID 38397230, 2024). "STAT4 is a transcription factor that plays a crucial role in developing autoimmune diseases." (PMID 38673659, 2024). "Therefore, the performed scientific researches contribute to establishing a relationship between STAT4 gene SNP (rs10181656, rs7574865, rs7601754, rs10168266) and autoimmune diseases." (PMID 38202017, 2023). "Therefore, highly correlated with the development of autoimmune diseases, STAT4 has a large potential to be a key regulator of graft-rejection activation." (PMID 35844542, 2022). "NETs have been shown to be important for autoimmune diseases, and considering the genetic link between STAT4 and various autoimmune diseases in human populations, it is possible that some of the impact of STAT4 on human disease is through activity in innate immune cells such as neutrophils." (PMID 34138758, 2021). "In vivo and in vitro studies in recent decades have suggested that STAT4 may induce inflammation and autoimmune diseases, inhibit tumor growth or promote tumors via regulating many facets of the innate and adaptive immune responses." (PMID 32226303, 2020). "Therefore it is an important mediator of the immune response and it is highly plausible that any change in STAT4 expression or activity can alter the function and response of the normal immune system, leading to immunosuppression or autoimmune disorders." (PMID 30666271, 2018). "Primary SS is an autoimmune disease with a genetic basis in which at least 40 gene risk factors may be involved, including BLK, IRF5, STAT4, and the HLA locus." (PMID 26379672, 2015). "Consequently, it is conceivable that deregulation of STAT4 activity or expression can alter the functioning of the immune system and, therefore, lead to autoimmune disorders or immunosuppression." (PMID 26569609, 2015). "After being identified as a risk gene for SLE and RA, STAT4 was also associated with susceptibility to a number of other autoimmune diseases, irrespective of ethnicity." (PMID 24632671, 2014).
autoimmune disease (continued). "There was a significant association of STAT4 rs7574865 with susceptibility to type-1 AIH even in the AIH patients without other overlapping autoimmune diseases." (PMID 23990947, 2013). "However, similar to STAT4, other IBD susceptibility genes such as IL23R, IL2/IL21, STAT3, and PTPN2 are associated with other autoimmune diseases." (PMID 20454450, 2010). "Recent results show that rs7574865, a variant allele of STAT4, confers an increased risk for both SLE and rheumatoid arthritis (RA), suggesting the involvement of common pathways of pathogenesis among these two autoimmune diseases." (PMID 18516230, 2008). "However, additional work is necessary to examine whether STAT4/5 exhibit sex‐specific regulation in autoimmune disease contexts." (PMID 41574968, 2026). "Consequently, a variation in STAT4 expression or activity might impact the regular immune system’s response and function, resulting in immunosuppression or autoimmune disorders." (PMID 38673659, 2024). "However, increased expression of STAT4 mRNA associated with T allele of rs7574865 has not been reported in patients with autoimmune disorders." (PMID 26569609, 2015). "Therefore, we hypothesized that STAT4 polymorphisms may overlap in genetic susceptibility between AIH and other autoimmune diseases." (PMID 23990947, 2013). "The STAT4 rs7574865T allele conferred risk for type-1 autoimmune hepatitis (OR = 1.61, 95% CI = 1.23–2.11; P = 0.001), and patients without accompanying autoimmune diseases exhibited an association with the rs7574865T allele (OR = 1.50, 95%CI = 1.13–1.99; P = 0.005)." (PMID 23990947, 2013). "STAT4 rs7574865 polymorphism in patients with type-1 AIH without other autoimmune diseases." (PMID 23990947, 2013). "Emerging evidence suggests that STAT4 and OPN interact in multiple biological processes, including T-cell differentiation, cytokine production, and autoimmune disease progression." (PMID 41222876, 2025). "Enrichment analysis revealed that 50 % of the shared genes (STAT4, TYK2, IL2RA, PTPN2, and STAT3) among autoimmune diseases belong to the JAK-STAT pathway." (PMID 39421031, 2024). "STAT4, an important member of the STAT family, has also been found to be closely related to the development of some tumors and autoimmune diseases." (PMID 38737443, 2024). "All STAT family members (STAT1, STAT2, STAT3, STAT4, STAT5A, STAT5B, and STAT6) are related to autoimmune diseases." (PMID 35204186, 2022). "On the other hand, high level of STAT4 leads to the production of high levels of IFN-γ that promotes Th1 and Th17 cell expansion, thus contributing to autoimmune disease." (PMID 31871930, 2019). "Th1 lineage specific transcription factors, T cell-specific transcription factors (T-bet), signal transducer and activator of transcription 4 (STAT4) and its promoting cytokine IL-12 are required for the development of the autoimmune disorder." (PMID 21858123, 2011). "Given their roles in autoimmunity, targeting STAT4 and OPN might be beneficial in autoimmune diseases." (PMID 41222876, 2025). "Most studies on STAT4 rs10181656, rs7601754, and rs10168266 relate to autoimmune diseases rather than tumorigenesis." (PMID 39597056, 2024). "Our results do not support a relevant role, similar to that described for other autoimmune diseases, of IL23R and STAT4 polymorphisms in the non-anterior uveitis genetic predisposition." (PMID 24312163, 2013). "The role of Th1 in autoimmune disorders is further confirmed by findings that mice lacking the Th1 lineage‐specific transcription factors, T‐bet and signal transducer and activator of transcription 4 (STAT4), are protected from the disease." (PMID 33135395, 2020). "However, our findings support the notion that SNPs and haplotypes in STAT4 may contribute to the development of PBC and other autoimmune diseases." (PMID 24648611, 2014).
systemic lupus erythematosus (52 papers, 2008 to 2026). An autoimmune multi-organ disease typically associated with vasculopathy and autoantibody production. "Preclinical studies indicate that STAT4 deficiency diminishes autoantibody production and glomerulonephritis in a lupus mouse model, corroborating our observations of STAT4-IL-6 interaction in pSS." (PMID 40772275, 2025). "STAT4 polymorphisms have been extensively studied in immune regulation disorders, including rheumatoid arthritis, polymyositis/dermatomyositis, and systemic lupus erythematosus." (PMID 39597056, 2024). "Another study showed that the STAT4 risk allele rs7574865[T] was associated with an elevated expression of IL-12 inducing IFN-γ production in lupus T cells." (PMID 37457579, 2023). "Several single nucleotide polymorphisms of the STAT4 gene have been associated with diseases such as rheumatoid arthritis, Sjogren’s, asthma, and systemic lupus erythematosus." (PMID 38275379, 2023). "Recent studies have identified many susceptibility loci of STAT4 in a variety of diseases including rheumatoid arthritis (RA), systemic lupus erythematosus (SLE) and BD." (PMID 38983559, 2022). "The deficiency of the Stat4 gene in lupus-prone mouse models has confirmed its major effect on lupus severity, leading to reduced autoantibody production and T cell activation." (PMID 36389689, 2022). "There are a few studies involving STAT4-deficient lupus-prone mice which demonstrate the role of STAT4 in autoantibody production only." (PMID 24741605, 2014). "The STAT4 has been found to be a susceptible gene in the development of systemic lupus erythematosus (SLE) in various populations." (PMID 22729903, 2012). "STAT4-deficiency is associated with accelerated renal disease and increased mortality in a murine lupus model, but with protective effects for arthritis in knockout mice." (PMID 18516230, 2008). "We show in this work that the STAT4 gene, very recently identified as a lupus risk gene, predisposes specifically to severe manifestations of lupus, including kidney disease." (PMID 18516230, 2008). "Recent data show that a lupus-associated SNP in the STAT4 gene leads to increased Stat4 expression, supporting the idea that higher Stat4 expression may promote autoimmunity." (PMID 28439269, 2017). "STAT4 has been demonstrated to be one of the strongest genetic susceptibility factors for systemic lupus erythematosus, and notably, patients with systemic lupus erythematosus with the STAT4 risk allele have a strikingly increased risk of cardiovascular disease." (PMID 28256502, 2017). "In fact, during the last decade, an increasing amount of evidence supports the notion that variants in the STAT4 gene are associated with an increased risk of developing rheumatoid arthritis (RA), systemic lupus erythematosus (SLE), type I diabetes, Sjögren syndrome, and systemic scleroderma (SSc)." (PMID 26569609, 2015). "The STAT4 null allele in lupus-prone mouse model confers reduced autoantibody production and glomerulonephritis, indicating that STAT4 may be involved in multiple SLE-associated phenotypes." (PMID 24741605, 2014). "Several genetic studies have identified polymorphic variants of the STAT4 gene, including rs7574865 and rs11889341, as susceptibility factors for RA and other autoimmune diseases such as systemic lupus erythematosus (SLE)." (PMID 41155304, 2025). "Previous studies have reported that STAT4 rs7574865 conferred the susceptibility to systemic lupus erythematosus (SLE)." (PMID 35493285, 2022). "Numerous studies have found that the STAT4 rs3821236 genetic polymorphism is associated with multiple disease risks, such as systemic lupus erythematosus (SLE), Systemic sclerosis and juvenile idiopathic arthritis." (PMID 34176465, 2021). "The aim of this study is to evaluate the association of STAT4 gene polymorphism with multiple sclerosis (MS) and juvenile onset systemic lupus erythematosus (JO-SLE) and its relation to disease severity." (PMID 29881250, 2018).
systemic lupus erythematosus (continued). "STAT4 polymorphism was significantly associated with multiple sclerosis (MS) and juvenile onset systemic lupus erythematosus patients (JO-SLE)." (PMID 29881250, 2018). "IL-12A has been linked to celiac disease and multiple sclerosis, whereas STAT-4 is involved in the development of systemic lupus erythematosus (SLE) and rheumatoid arthritis (RA)." (PMID 25803105, 2015). "Conditions such as systemic lupus erythematosus (SLE), rheumatoid arthritis (RA), inflammatory bowel disease (IBD), and Sjögren's syndrome have been linked to SNPs in the STAT4 gene." (PMID 41473684, 2025). "Stat4 rs7574865 is related to autoimmune diseases such as multiple sclerosis, systemic lupus erythematosus (SLE), rheumatoid arthritis (RA), and primary Sjogren’s syndrome." (PMID 35136014, 2022). "In our previous works, we described associations between SNPs in the STAT4, IL10, TRAF3IP2, and HCP5 (HLA complex P5) genes and systemic lupus erythematosus (SLE) susceptibility." (PMID 30882006, 2019). "Both STAT1 and STAT4 have been reported to be related to autoantibody production and renal involvement in either lupus mice or SLE patients." (PMID 29793537, 2018). "Lupus-associated single-nucleotide polymorphisms in IRF7, IRF5, and STAT4 are related to elevated levels of IFN-α, and some SLE risk haplotypes of IRF5 have been shown to be associated with increased IFN-α expression in SLE." (PMID 29052537, 2017). "STAT4 haplotype characterized by rs7574865 exhibited strong linkage with rheumatoid arthritis (RA), systemic lupus erythematosus (SLE), and autoimmune disease: e.g., systemic sclerosis, Sjögren’s syndrome, Type 1 diabetes." (PMID 25520922, 2014). "Interestingly, the presence of two STAT4 independent functional genetic variants associated with systemic lupus erythematosus (SLE), both affecting the STAT4 levels, has been recently evidenced by fine mapping." (PMID 24312163, 2013). "These include PTPN22, associated with systemic lupus erythematosus (SLE), rheumatoid arthritis (RA), T1D, and Graves' Disease (GD), STAT4, associated with SLE and RA, and the IL7R and KIAA0350 gene regions, which are shared between T1D and MS." (PMID 19119414, 2009). "However, when exposed to type I IFN, the cells switched to a ‘lupus phenotype’ with increased STAT4 phosphorylation." (PMID 41503065, 2025). "Interestingly, knockout of the Stat4 gene reduces autoantibody production in lupus-prone B6.TC mice." (PMID 28439269, 2017). "Different risk alleles susceptibility loci, lupus-susceptibility genes, and SNPs have also been identified in SLE patients such as interferon regulatory factor (IRF5); HLA-DR2 and HLA-DR3, Ifi202 of Ifi200-family, PTPN22, CTLA4, STAT4 and BANK1, TLR 7, 8, 9, etc.." (PMID 26779182, 2015).
rheumatoid arthritis (51 papers, 2008 to 2026). A chronic, systemic autoimmune disorder characterized by inflammation in the synovial membranes and articular surfaces. "To date, several STAT4 genetic variants have been identified, including rs7574865 and rs11889341, which are associated with an increased risk of developing rheumatoid arthritis." (PMID 41155304, 2025). "The results show an association between STAT4 haplotype (rs11889341, rs7574865, rs8179673, and rs10181656) and type 1 diabetes and rheumatoid arthritis." (PMID 38202017, 2023). "STAT4 is a risk factor for inflammatory diseases such as rheumatoid arthritis and lupus erythematosus, and is initially identified as an important immunoregulator, which regulates various cytokine or chemokine production by immune cells." (PMID 37194066, 2023). "We report that variants in the STAT4 gene, previously associated with other autoimmune conditions including rheumatoid arthritis and SLE, appear to confer susceptibility to AAD, as demonstrated by data derived from the Italian, Norwegian and Swedish populations studied." (PMID 24614117, 2014). "The minor allele of this SNP, in addition to three others in intron 3 of STAT4, was also associated with rheumatoid arthritis in the Korean population (P = 0.0065, OR 1.27 [95% CI 1.11–1.45]) and with primary Sjögren's syndrome in a small study (P = 0.01, OR 1.47 [95% CI 1.09–1.97])." (PMID 24614117, 2014). "STAT4 rs7574865 polymorphism has been evidently associated with susceptibility to Rheumatoid Arthritis (RA) in European and Eastern Asian populations, whereas studies in other countries reported otherwise." (PMID 30505369, 2018). "STAT4 SNPs have been already described in other autoimmune conditions such as rheumatoid arthritis and SLE, and an association between the STAT4 rs7574865 and the susceptibility to SS has been reported too." (PMID 30882006, 2019). "Variation at the STAT4 locus is well established as having a role in several different autoimmune conditions including rheumatoid arthritis, SLE and primary Sjögren's disease." (PMID 24614117, 2014). "The number of copies of the HLA-DRB1 shared epitope, and the minor alleles of the STAT4 rs7574865 and the PTPN22 rs2476601 polymorphisms have all been linked with an increased risk of developing rheumatoid arthritis." (PMID 22937072, 2012). "Recently, a polymorphism of the STAT4 gene on chromosome 2q has been strongly implicated in the risk for both SLE and rheumatoid arthritis." (PMID 18516230, 2008). "Recently, it has been reported that the single nucleotide polymorphisms (SNPs) of STAT4, PTPN2, PSORS1C1, and TRAF3IP2RA genes are associated with the clinical efficacy of tumor necrosis factor (TNF) inhibitors in the treatment of rheumatoid arthritis (RA) patients." (PMID 31709198, 2019). "This study investigated five confirmed rheumatoid arthritis (RA) susceptibility genes/loci (HLA-DRB1, PTPN22, STAT4, OLIG3/TNFAIP3 and TRAF1/C5) for association with susceptibility and severity in an inception cohort." (PMID 20353580, 2010). "The STAT4 gene has been related to an increased vulnerability to autoimmune illnesses such as SLE, primary Gren’s syndrome, rheumatoid arthritis, and thyroid problems." (PMID 38003408, 2023). "At the same time, some are typically related to other autoimmune diseases as diabetes or rheumatoid arthritis (RA) (PTPN22 and STAT4)." (PMID 28350323, 2017). "Additionally, links to autoimmune and inflammatory diseases, including rheumatoid arthritis and psoriasis, were supported by connections to JAK inhibitors and immune-modulatory genes like STAT4." (PMID 40732226, 2025).